HOXB7 (homeobox B7)
Diseases named in the same sentence as HOXB7 in open-access papers (continued):
Sharing a sentence is not in itself a finding about the gene and the disease.
melanoma (16 papers, 2009 to 2025). A malignant, usually aggressive tumor composed of atypical, neoplastic melanocytes. "Moreover, PBX1 interacts with HOXB7 in melanoma cells and the downregulation of Pbx1 causes Hoxb7 and target gene downregulation, including bFGF, Ang-2, and Mmp9." (PMID 33402862, 2020). "The HOXB7 gene has been found to be constitutively expressed in primary melanoma tumors and their metastases, as well as in 25 melanoma cell lines." (PMID 33171691, 2020). "To demonstrate that the HOXB7/PBX2 dimer can activate the transcription of miR-221&222 in melanoma, we selected the Me1402/R cell line for HOXB7 transient over-expression (right)." (PMID 23400877, 2013). "Our findings, besides suggesting the potential therapeutic of HXR9 or its derivatives in malignant melanoma, suggest the disruption of the HOXB7/PBX2 complexes, miR-221&222 inhibition or even better their combination, as innovative therapeutic approaches." (PMID 23400877, 2013). "Although we found HOXB7 mRNA expression in melanocytes and in all the analyzed melanomas, HOXB7 protein showed a statistically significant higher expression in melanoma cell lines compared to the normal counterpart." (PMID 23400877, 2013). "Studies have shown that HOXB7 binds with members of the PBX family in melanoma, promoting the expression of miR-221 and miR-222, which in turn regulate downstream factors, leading to increased cell proliferation and infiltration, blocking cell differentiation, and reducing cell apoptosis." (PMID 39980564, 2025). "Some epidemiological studies have demonstrated that overexpression of HOXB7 is correlated with poor prognosis in breast, colorectal, and gastric cancer, and upregulation of HOXB7 mRNA and/or protein expression has been reported in melanoma, ovarian cancer, and esophageal squamous cell carcinoma." (PMID 36718148, 2023). "The HOXB7/FGF2 interaction has already been described in melanoma and BT474 cells." (PMID 34063128, 2021). "Moreover, HoxB3 promotes capillary morphogenesis during angiogenesis, and HoxB7 directly upregulates the expression of bFGF in human melanoma cells; the activation of bFGF induces EC proliferation in vitro." (PMID 19825192, 2009). "PBX2 formed a dimer with HOXB7, and the dimer decreased the expression of c‐FOS by upregulated miR‐221 and miR‐222 in melanoma cells." (PMID 35068042, 2022). "HXR9 treatment results in the downregulation of miR-221&222 in human melanoma cells as a consequence of HOXB7/PBX2 heterodimer disruption and the subsequent degradation of HOXB7 and PBX2 proteins." (PMID 23400877, 2013). "Results confirmed lower HOXB7 and higher c-FOS in primary respect to advanced melanomas." (PMID 23400877, 2013). "The potential value of the HOXB7/PBX2→miR-221&222→c-FOS pathway suggests the disruption of the HOXB7/PBX2 complexes, miR-221&222 inhibition or their combination as innovative therapeutic approaches in melanoma." (PMID 23400877, 2013). "In view of the requirement of HOX cofactors, such as PBX proteins, for HOXB7 oncogenic activity, we measured the levels of PBX1 and PBX2 proteins in melanoma cell lines, representative of early and advanced stages, showing that PBX2 protein was more abundant than PBX1 (bottom)." (PMID 23400877, 2013). "Retroviral transduction of PLZF expression in melanoma cells resulted in a more differentiated, less malignant phenotype both in vitro and in vivo which appears to be mediated by inhibition of the Pre-B-Cell Leukemia Homeobox 1 (PBX1) and Homeobox B7 (HOXB7) complex." (PMID 29050363, 2017).
pancreatic cancer (15 papers, 2012 to 2025). "For example, HOXB7 is dysregulated in tumors, such as colorectal and pancreatic cancers and is associated with differentiation and tumor grade." (PMID 37534217, 2023). "It was reported that miR-337 inhibits proliferation and invasion of pancreatic tumor cells via targeting HOXB7." (PMID 29659498, 2018). "In summary, these results demonstrated that overexpression of miR-337 can suppress cell proliferation, migration, and invasion in human pancreatic cancer cell lines by targeting HOXB7." (PMID 25183455, 2014). "HOXB7 was found to be involved in pancreatic cancer cell proliferation and apoptosis by siRNA assay." (PMID 24641834, 2014). "For this reason, the role of miR-337 on HOXB7 expression and the effects of miR-337 on proliferation and invasion in human pancreatic cancer cells in vitro were here examined." (PMID 25183455, 2014). "Similarly, in pancreatic cancer, HOXB7 knockdown reduced ERK phosphorylation, affecting the Rho family of GTPases and consequently diminishing cell protrusions and invasiveness." (PMID 41040515, 2025). "Furthermore, HOXB7 is overexpressed in solid tumors such as esophageal cancer, intrahepatic cholangiocarcinoma, cutaneous squamous cell carcinoma, osteosarcoma, and pancreatic cancer, suggesting a cancer-promoting role 49-53." (PMID 40657360, 2025). "The Epidermal Growth Factor Receptor (EGFR) overexpression is recognized as a driver mechanism in the initiation, progression, and therapy resistance of several carcinomas such as lung, breast, and pancreatic cancers, added the interaction HOXB7/EGFR promoter region already demonstrated." (PMID 34063128, 2021). "HOXB7 is another component of the extensive network of molecules involved in the pathobiology of pancreatic cancer and might constitute a promising target for future biological therapies." (PMID 24088503, 2013). "Interestingly, HOXB7 expression is also high in liver and pancreatic cancers." (PMID 34063128, 2021). "In PDAC, aberrant expression of several HOX transcription factors has been described and functional studies have shown that HOXA10, HOXB7, and HOXC11 promote pancreatic cancer development while HOXA1, HOXB1, and HOXB3 act as tumor-suppressors." (PMID 40619489, 2025). "IGF2BP3 (p<0.0001), HOXB7 (p<0.0001), and NEK2 (p<0.0001) mRNA expression levels were significantly increased in patients with cholangiocarcinoma or pancreatic cancer." (PMID 22879911, 2012). "It has previously been reported that some HOX genes are overexpressed in pancreatic tumors and they include HOXA10, HOXB7 and HOXB2, and transfection of Panc1 cells with siHOTTIP slightly decreased expression of HOXB7 but significantly decreased HOXA10 (>80%) and HOXB2 (>60%)." (PMID 25912306, 2015).
gastric cancer (12 papers, 2016 to 2025). A primary or metastatic malignant neoplasm involving the stomach. "Psoralen, a natural photosensitizing drug, triggers the apoptosis of gastric cancer cells to alleviate cisplatin resistance by upregulating miR-196a-5p and downregulating homeobox B7 (HOXB7) and HER2 expression." (PMID 36612314, 2023). "HOXB7 up-regulation has been demonstrated in gastric cancer and shown to indicate poor prognosis in gastric cancer patients." (PMID 28646927, 2017). "It has also been reported that gastric cancer cell metastasis is promoted by HOXB7 via the PI3K/AKT pathway." (PMID 28646927, 2017). "In gastric cancer, HOXB7 disrupted the F-actin structure and promoted the EMT." (PMID 41040515, 2025). "For example, HOXB7 is a carcinogenic factor that promotes gastric cancer development." (PMID 40657360, 2025). "For example, HOXB7 activates the FGF-MAPK (fibroblast growth factor- mitogen-activated protein kinases) and PI3K/Akt (phosphoinositide 3-kinase/protein kinase B) signaling pathways in breast and gastric cancer, respectively." (PMID 30974862, 2019).
ovarian carcinoma (12 papers, 2009 to 2023). A malignant neoplasm originating from the surface ovarian epithelium. "The Naora team undertook a systematic search for a diagnostic antigen via SEREX methodology (discussed previously) and found HOXB7 was a potential diagnostic antigen with 13/39 ovarian cancer patients producing antibodies against it versus 1/29 healthy females." (PMID 31382546, 2019). "In ovarian cancer, HOXB7 can enhance cell proliferation by promoting ovarian cancer cells to secrete more bFGF." (PMID 34306077, 2021). "They found that HOXB7 was a valuable target with 13/39 ovarian cancer patient serum reacting to HOXB7 protein, compared to 1/29 healthy controls." (PMID 31382546, 2019). "For example, Module 37 includes four HOX family genes (HOXB2, HOXB4, HOXB6 and HOXB7) that all have been extensively reported to be related with ovarian cancer." (PMID 22863767, 2012). "HOXB7 and HOXB13 have been linked to increased instances of metastasis in breast and ovarian cancers and their overexpression in cell lines enhances many features of EMT." (PMID 21433221, 2011). "Ovarian carcinomas were found to express HOXB7, a product of a homeobox gene, at markedly higher levels than normal OSE." (PMID 20145720, 2009). "In ovarian cancer cells, the expression of miR-513a-3p is significantly decreased, miR-513a-3p inhibits epithelial–mesenchymal transition and promotes sensitivity of ovarian cancer cells to cisplatin by targeting HOXB7." (PMID 35545766, 2022). "HOXB7 expression could promote cell growth by triggering both intracrine and autocrine bFGF growth stimulatory pathways in ovarian carcinomas." (PMID 26076456, 2015). "In addition to promoting proliferation, HOXB7 and HOXB13 are also thought to be associated with the invasive characteristics of ovarian cancer cells." (PMID 21906307, 2011). "HOXB7 was one of the HOX genes found in this screen, with significant serological reactivity to HOXB7 in 13 of the 39 ovarian cancer patients and in 1 healthy female, suggesting the detection of anti-HOXB7 antibodies could act as a possible diagnostic tool." (PMID 21906307, 2011). "This indicates that HOXB7 overexpression could play a significant role in growth of ovarian carcinomas." (PMID 20145720, 2009). "Many studies have found that HOXB cluster members are involved in the tumorigenesis or progression of ovarian cancer, including HOXB2, HOXB3, HOXB4, HOXB7, and HOXB8." (PMID 33815481, 2021). "HOX genes showing markedly higher expression in ovarian cancer cell lines and cancer tissue specimens compared to the normal ovaries also have the potential of acting as prognostic markers, these include HOXB4 and HOXB7." (PMID 21906307, 2011).
esophageal squamous cell carcinoma (11 papers, 2014 to 2025). Esophageal squamous cell carcinoma (ESCC) is a type of esophageal carcinoma (EC) that can affect any part of the esophagus, but is usually located in the upper or middle third. "However, little is known regarding the association between HOXB7 and chemotherapy resistance in esophageal squamous cell carcinoma (ESCC)." (PMID 31568655, 2020). "Deregulation of HOXB7 expression in esophageal squamous cell carcinoma predicted poor outcomes of patients." (PMID 28646927, 2017). "We observed abnormal HOXB7 expression in esophageal squamous cell carcinoma (ESCC) previously." (PMID 26076456, 2015). "For example, HOXB7 is an essential downstream target of BBOX1-AS1, and HOXB7 is involved in the activation of the Wnt/β-catenin signaling pathway, contributing to malignant phenotypes in esophageal squamous cell carcinoma." (PMID 37925403, 2023). "Similarly, HOXB cluster dysregulation, and dysregulation of the HOX genes in general, are closely linked to cancer, though these specific genes (HOXB7, HOXB8, and HOXB9) have not been shown in specific relation to esophageal squamous cell carcinomas." (PMID 38886487, 2024).
cervical cancer (7 papers, 2013 to 2024). A primary or metastatic malignant neoplasm involving the cervix. "On the other hand, micro-RNA-196 down regulation is implicated in homeobox B7-vascular endothelial growth factor pathway, which plays an important role in cervical cancer progression." (PMID 29783999, 2018). "For instance, in cervical cancer, hsa_circ_0009035 promotes tumor progression and radioresistance via the miR-889-3p/HOXB7 axis." (PMID 38632984, 2024). "In conclusion, we report for the first time that miR-196b is a novel tumor suppressor in cervical cancer, by regulating the transcription factor HOXB7, which in turn, induced VEGF expression." (PMID 23861821, 2013). "In this current study, we provide evidence for an alternate mechanism for HOXB7 deregulation, via miR-196b, in cervical cancer." (PMID 23861821, 2013). "Since HOXB7 is a transcription factor, it was necessary to determine which gene(s) regulated by HOXB7 could be relevant in this context for cervical cancer." (PMID 23861821, 2013). "Our findings have demonstrated that the miR-196b/HOXB7/VEGF pathway plays an important role in cervical cancer progression; hence targeting this pathway could be a promising therapeutic strategy for the future management of this disease." (PMID 23861821, 2013). "In this study, we identified that miR-196b was significantly down-regulated in both cervical cancer cell lines and primary tissues, which promoted tumour cell proliferation, migration, invasion, and angiogenesis, mediated through VEGF regulation by HOXB7." (PMID 23861821, 2013). "Furthermore, we identified the HOXB7 transcription factor as a novel, direct and specific target of miR-196b, which in turn, regulates VEGF in cervical cancer." (PMID 23861821, 2013).
glioma (7 papers, 2021 to 2025). A benign or malignant brain and spinal cord tumor that arises from glial cells (astrocytes, oligodendrocytes, ependymal cells). "In glioblastoma, circ_0074362 was closely linked to miR-1236-3p, which targets the gene HOXB7, resulting in glioma cell advancement." (PMID 40429981, 2025). "High HOXB7 expression is significantly positively correlated with GBM and IDH1 wild type status, which indicates that HOXB7 functions as an oncogene in gliomas." (PMID 34458259, 2021). "The results showed that the expression of HOXB7 mRNA was significantly lower in 1p/19q codeletion gliomas (oligodendroglioma) (p < 0.0001)." (PMID 34458259, 2021). "In the current study, we utilized two independent cohorts to evaluate and validate the role of HOXB7 in prognosticating patients with glioma." (PMID 34458259, 2021). "Our latest research also showed that HOXB8, another member of the homeobox B family, is a crucial contributor to the aggressiveness of GBM, but the expression of HOXB7 in human glioma remains uncharacterized." (PMID 34458259, 2021). "Further multivariate Cox regression analyses showed that HOXB7 was an independent predictive factor of poor prognosis in all grade glioma patients." (PMID 34458259, 2021). "First, we investigated the expression pattern of HOXB7 in gliomas by analyzing the mRNA expression level of HOXB7 based on the RNA-seq data of 325 samples from the CGGA database." (PMID 34458259, 2021). "The circRNA–miRNA–gene regulatory networks have largely found in previous exploration of circRNAs in glioma, such as circ_0074362/miR-1236-3p/HOXB7, circMAN2B2/miR-1205/SA00A8 and circ_0088732/miR-661/RAB3D." (PMID 34017919, 2021). "We noted that in lower grade glioma patients, the survival time with high expression of HOXB7 subgroup was similar to that of the IDH1 wild type subgroup." (PMID 34458259, 2021). "The effect of circ_0074362 on glioma progression was achieved through depending on the miR-1236-3p/HOXB7 axis." (PMID 34057019, 2021). "Survival curve analysis showed that high HOXB7 expression confers a reduced survival time in all grade glioma and lower grade glioma patients." (PMID 34458259, 2021). "As anticipated, the expression trend of HOXB7 protein was consistent with that of RNA level in different WHO grades or molecular types of gliomas (R = 0.728, p < 0.001)." (PMID 34458259, 2021). "Taking these two types of gliomas alone, the sensitivity and specificity of HOXB7 protein deletion in oligodendroglioma were 90.9% (20/22) and 87.0% (20/23), respectively." (PMID 34458259, 2021). "In glioma, HOXB7 facilitated invasion and migration of tumor cells by activating the Wnt signaling, while obviously related to lymph node metastasis or distant metastasis." (PMID 34303375, 2021). "The mRNA and protein expression levels of HOXB7 in different clinical and molecular glioma subtypes were analyzed." (PMID 34458259, 2021). "In the same WHO grade glioma, the HOXB7 protein was expressed more highly in IDH1 wild type than that in IDH1 mutant type." (PMID 34458259, 2021). "For example, in glioma, HOXB7 promoted invasion and migration by regulating the Wnt/β-catenin signaling pathway in glioma cells, and was significantly correlated with tumor lymph node metastasis or distant metastasis." (PMID 34303375, 2021). "In this study, HOXB7 mRNA and protein expression levels were analyzed in 401 gliomas from the CGGA RNA-seq database (325 cases) and our hospital (76 cases)." (PMID 34458259, 2021). "Moreover, HOXB7 mRNA and protein levels are significantly down regulated in 1p/19q codeletion gliomas." (PMID 34458259, 2021). "In conclusion, HOXB7 is an independent predictor of poor prognosis in all grade gliomas." (PMID 34458259, 2021). "We also examined the prognostic value of HOXB7 in glioma patients with different WHO grades." (PMID 34458259, 2021). "However, there are few reports on the relationship between HOXB7 and gliomas." (PMID 34458259, 2021).
glioma (continued). "In this study, HOXB7 was highly expressed in GBM and IDH1 wild type gliomas at both mRNA and protein levels." (PMID 34458259, 2021). "HOXB7 expression, at both mRNA and protein levels, were upregulated in glioblastoma (GBM) and isocitrate dehydrogenase 1 (IDH1) wild-type glioma tissues." (PMID 34458259, 2021). "In both WHO all-grade gliomas and within the same WHO grade gliomas, the level of HOXB7 mRNA was more highly expressed in IDH1 wild type gliomas than in IDH1 mutant types (p < 0.0001)." (PMID 34458259, 2021). "Therefore, we analyzed the correlation between HOXB7 RNA level and 1p/19q deletion status based on the RNA SEQ information of 325 cases of gliomas in the CGGA data sets." (PMID 34458259, 2021). "The patients with HOXB7 high expression, IDH1 wild-type and 1p/19q non-codeletion subgroups all had similar survival trends, which further illustrate the association between HOXB7 and IDH1 wild-type gliomas, as well as 1p/19q non-codeletion gliomas." (PMID 34458259, 2021).